ERBB2 (erb-b2 receptor tyrosine kinase 2)
Diseases named in the same sentence as ERBB2 in open-access papers (continued):
Sharing a sentence is not in itself a finding about the gene and the disease.
breast cancer (continued). "The I-SPY2 trial studied the benefits of adding pembrolizumab to standard NACT for high-risk women with stage II or III, ERBB2-negative breast cancer." (PMID 32542231, 2020). "Notably, LDL-C has been confirmed to be able to induce a proliferation and metastasis of breast cancer by activating ErbB2 pathway and reducing the expression of adhesion molecule." (PMID 33585179, 2020). "Thus HER3 is necessary for HER2 oncogenic activity, and both HER2 and HER3 are therapeutic targets in ERBB2-amplified breast cancer." (PMID 32782013, 2020). "PAK4, a kinase that can phosphorylate MZF1 serine 27 in response to ErbB2 activation, is considered as a good target for the treatment of a variety of solid cancers including breast cancer, and its inhibition for this purpose has been patented by Hoffman-La Roche and Genentech." (PMID 31963147, 2020). "In addition, the RANK/RANKL axis also has a crucial impact on the occurrence of ErbB2-positive breast cancer." (PMID 31933009, 2020). "We used data from US population-based Surveillance Epidemiology and End Results (SEER) cancer registries to examine trends in the incidence of breast cancer by age and racial/ethnic groups from 2010 to 2016 for 4 molecular subtypes, defined by joint expression of hormone receptor and ERBB2 status." (PMID 32804214, 2020). "ERBB2, a common oncogene that has been used as one of the key prognostic and treatment indicators in breast cancer, exhibits an overexpressed level in approximately 25–30% of breast cancers and confers a worse biological effect." (PMID 32793288, 2020). "Loss of PTPN12 promotes in vivo tumor progression of the implanted breast cancer cells, which express a constitutively active form of ErbB2 (CA-ErbB2), and correlates with the impaired feedback regulation of RTKs, thereby resulting in their aberrant activation." (PMID 33050232, 2020). "However, the alterations most studied and most directly involved in the progression and development of breast cancer pathways are those mediated by the ER and human epidermal growth factor type-2 receptors (HER2/Neu or c-ErbB2)." (PMID 32211045, 2020). "ErBB2 degradation by autophagy may alter the sensitivity to the humanized monoclonal antibody trastuzumab in breast cancer." (PMID 31896739, 2020). "While we utilized MMTV/ErbB2 mice as a model for breast cancer, a similar mechanism may take place in other subtypes of breast cancer." (PMID 33267874, 2020). "Thus, whereas LRIG1 suppresses ERBB2 expression and the proliferation of ERBB2-positive breast cancer cells, ERBB2 itself downregulates LRIG1 levels in breast cancer cells, thereby canceling the tumor-suppressive function of LRIG1." (PMID 32448168, 2020). "Moreover, we found that upregulation of these proteins in EVs derived from the blood of a pilot cohort of breast cancer patients with metastatic ErbB2-positive breast cancer tends to correlate with trastuzumab sensitivity of patients’ tumors." (PMID 33023655, 2020). "More importantly, initial clinical trials with the HSP90 inhibitors tanespimycin (17-AAG) and alvespimycin (17-DMAG), two derivatives of the antibiotic geldanamycin, provided additional lines of evidence that supports the validity of targeting HSP90 in ErbB2-positive breast cancers." (PMID 32327714, 2020). "Finally, multivariate analysis indicated that high inclusion levels of ECT2-Ex5 were an independent predictive marker of bad prognosis in the subgroup of 120 HR+ERBB2- breast cancer patients treated with chemotherapy." (PMID 31943118, 2020).
breast cancer (continued). "For 13 out of the 14 cases, ERBB2 amplification was confirmed by exome sequencing along with amplifications and mutations in a range of genes previously implicated by the TCGA and ICGC breast cancer studies 19,20." (PMID 31988290, 2020). "Some kinase inhibitors have been approved for anti-cancer therapies, for example, BCR–ABL inhibitors have been approved for chronic myeloid leukemia, BRAF inhibitors have been approved for melanoma and HER2 (also known as ERBB2) inhibitors have been approved breast cancer." (PMID 33087151, 2020). "In addition, we observed that upregulation of these proteins in the blood-derived EVs seems to correlate with clinical benefit that a pilot cohort of breast cancer patients with metastatic ErbB2-positive tumors received from trastuzumab-based therapies." (PMID 33023655, 2020). "Indeed, 20% of ErbB2 breast cancer patients present primary resistance to ErbB2-targeting agents (e.g., trastuzumab, prastuzumab, lapatinib), and 70% of patients with ErbB2 metastatic cancer present acquired resistance." (PMID 32695336, 2020). "Alterations of human epidermal growth factor receptor 2 (HER2) proto-oncogene (also known as erbB-2 or HER2/neu) have been implicated in the carcinogenesis and prognosis of breast cancer; they have also been thought to play a critical role in both breast cancer development and progression." (PMID 33331402, 2020). "It has been reported that the immunophilin Pin1 is overexpressed in breast cancer and that its up-regulation is prevalent in ERBB2-positive tumours; however, its silencing or functional inhibition does not potentiate TZ activity, possibly because it accelerates receptor degradation." (PMID 33037285, 2020). "This is the case for the sensitivity to HER2-inhibitors for tumors with ERBB2 amplification in breast cancer, the vemurafenib sensitivity of BRAF-mutant cells in melanoma, or the relevance of EGFR mutation for EGFR-inhibitor treatments in non-small cell lung cancer (NSCLC)." (PMID 32645997, 2020). "Triple-negative breast cancer (TNBC) is a highly heterogeneous disease, representing the most aggressive breast cancer (BC) subtype with limited treatment options due to a lack of estrogen receptor alpha (ERα), progesterone receptor (PR), and Erb-B2 receptor tyrosine kinase 2 (HER2/neu) expression." (PMID 32260128, 2020). "The amplification of the Human Epidermal Growth Factor Receptor-2, ErbB2 (HER2), identified in 15 to 20% of breast cancers (BCs), is a factor of tumor aggressiveness that has been associated with more frequent relapses and poor survival rates since a long time." (PMID 32545895, 2020). "Following MEMO1′s isolation from this phosphorylated residue, it quickly became apparent—utilizing breast carcinoma cell lines—that the cellular machinery required for cell migration, initiated by ERBB2 signaling, was defective when cells were depleted of MEMO1." (PMID 33172038, 2020). "The specific role of p140Cap in curbing the aggressiveness of ERBB2-amplified breast cancers may rely on its ability to impinge on specific molecular pathways." (PMID 31681758, 2019). "Interestingly, STARD10 has been described to be highly expressed in 35–40% of ERBB2-positive breast cancers." (PMID 30611309, 2019). "In breast cancer, the triple-negative (TN) and Human Epidermal Growth Factor Receptor-2 HER2/ERBB2-positive molecular subtypes are at a higher risk of BM, but the molecular bases of this tropism remain poorly understood." (PMID 31086113, 2019). "Overall this study supports p130Cas/ErbB2 complex as a potential breast cancer target and shows the druggability of this protein-protein interaction (PPI) that might benefit of a more advanced optimization effort for therapeutic applications." (PMID 30816273, 2019). "It is illustrated that PPAR-γ overexpressed in ERBB2-positive breast cancer cells." (PMID 31752829, 2019). "The HER2/ERBB2 oncogene is overexpressed in approximately 25% of breast cancer cases." (PMID 30906568, 2019).
breast cancer (continued). "In this work, the ERBB2 and TOP2α DNA and RNA status were analyzed and compared between 27 fresh feline mammary tumor (FMTs) samples and disease-free tissues (DFT) collected from the same animals, being these profiles integrated with clinicopathological features." (PMID 31301170, 2019). "Moreover, the ERBB2/Grb7-mediated Shc/Ras signal transduction cascade has been reported to regulate the proliferation of ERBB2-overexpressing breast cancers." (PMID 31083325, 2019). "Indeed, PD-L1 has been recently reported as a potential target for breast cancer, due to its high expression in both ErbB2-positive and Triple Negative Breast Cancer." (PMID 31511565, 2019). "Because BCLIN25 is a HER2 subtype-specific-lincRNA in breast cancer, we wondered whether ERBB2 is a downstream target of BCLIN25." (PMID 31801944, 2019). "The resultant membrane physical properties facilitated the internalization and subsequent degradation of cell surface ErbB2, which synergized with lapatinib or neratinib to elicit potent inhibitory effects on ErbB2-positive breast cancer growth both in vitro and in vivo." (PMID 30786890, 2019). "For instance, in the case of ERBB2, a gene that is known to be amplified in breast cancer, we could observe that many samples in regime 1 indeed have an amplification in ERBB2." (PMID 31072345, 2019). "The same effect was confirmed also in the ErbB2-positive breast cancer cell line BT-474, supporting the notion that NRF2 inhibition with RNAi might be a therapeutic strategy to limit tumor growth and enhance sensitivity to taxane-based chemotherapy." (PMID 31097977, 2019). "Alterations in both, ERBB2 and PIK3CA, cover 14% of biomarkers associated to breast cancer." (PMID 31169290, 2019). "ERBB-2 is overexpressed in about 20% of breast cancers (BCs), indicating poor prognosis." (PMID 31796128, 2019). "Triple-negative breast cancer (TNBC), characterized by lack of expression of the estrogen (ER), progesterone (PgR), and erb-b2 receptor tyrosine kinase 2 (HER2) receptors, is a particularly problematic form of breast cancer due to aggressive growth, high recurrence rates and poor long-term survival." (PMID 31619719, 2019). "Amplified ERBB2 (17q12) is the main oncogenic driver in one third of breast cancer cases." (PMID 31817861, 2019). "Our data suggest that the inhibition of ErbB2-p130Cas interaction might impact on both breast cancer cell proliferation and resistance to Trastuzumab, opening up new therapeutic perspectives." (PMID 30816273, 2019). "In addition, we established CLCN3 shRNA or control shRNA stably expressing cells using the ErbB2-overexpressing breast cancer cell lines SKBR3 and MDA-MB-453 and analyzed the 3D spheroid proliferation of these stable cells." (PMID 31608175, 2019). "PTP1B was well studied in breast cancer in the aspect of synergizing with the ErbB2 oncogene." (PMID 31695578, 2019). "The current standard of care for the treatment of metastatic ERBB2 breast cancer is the combination of pertuzumab, trastuzumab and a taxane in the first-line setting and T-DM1 (Kadcyla, a trastuzumab-emtansine chemotherapy conjugate), in the second line setting." (PMID 30898150, 2019). "Thus, the BCLIN25-miR-125b-ERBB2 axis was identified to upregulate ERBB2 expression, thereby indicating BCLIN25 as a bona fide MS-lincRNA for HER2 breast cancer." (PMID 31801944, 2019). "Since PD-L1 plays a critical role in breast cancer, as it is expressed at high levels by both ErbB2-positive and TNBC, and a high proportion of PD-L1-positive tumors are infiltrated with PD-1-positive lymphocytes, it can be considered as a potential target for breast cancer treatments." (PMID 31511565, 2019).
breast cancer (continued). "The combination of doxo with trastuzumab, the humanized monoclonal antibody against the erythroblastic leukemia viral oncogene homolog 2 (ErbB2), also known as epidermal growth factor receptor-2 (HER2), demonstrated a significant reduction in morbidity and mortality in breast cancer patients." (PMID 31052420, 2019). "Successful applications of Abl inhibitor for BCR-Abl-dependent chronic myeloid leukemia, EGFR inhibitors for EGFR mutation dependent non-small cell lung cancer, and ErbB2 inhibitors for ErbB2-dependnet breast cancer are all examples of both the power of targeted therapy and the challenge it faces." (PMID 30754629, 2019). "Indeed, activation of NF-kB - the major downstream mediator of RANK signaling - has been associated with cell survival, proliferation, and invasion, as well as resistance to anti-ErbB2 agents in ErbB2-positive breast cancers." (PMID 30621730, 2019). "Having disclosed the correlation between cholesterol content in the cell membrane and the surface levels of ErbB2 receptors, we next sought to investigate the influence of the cholesterol-lowering drug lovastatin on the in vitro growth of ErbB2-positive breast cancer cell lines." (PMID 30786890, 2019). "Moreover, estrogen-related receptor α (ERRα) is co-activated by peroxisome proliferator-activated receptor gamma coactivator (PGC)-1α, a crucial regulator for Gln metabolism genes in ERBB2+ breast cancer." (PMID 31429768, 2019). "Lapatinib is a dual inhibitor of ErbB1/ErbB2 which is used to treat ErbB2-positive breast cancer." (PMID 31905843, 2019). "Hence, the overexpression of ErbB2 inversely correlates with patient prognosis, while ErbB2 has proved as a top therapeutic target in breast cancer treatment with multiple ErbB2-targeted therapies received FDA approvals." (PMID 30786890, 2019). "This increased stabilization of ErbB2 by p130Cas might be the crucial event driving breast cancer progression and resistance, strengthening the relevance of p130Cas as putative therapeutic target to overcome resistance to Trastuzumab5." (PMID 30816273, 2019). "ErbB2 has proven as a top therapeutic target in the clinical treatment of breast cancer." (PMID 30786890, 2019). "Indeed, both GRB7 and ERBB2 are key genes that predict the recurrence of breast cancer in clinical trials." (PMID 31083325, 2019). "In addition, we previously reported that ErbB2 signaling epigenetically suppresses miR-205-5p transcription via the Ras/Raf/MEK/ERK pathway in breast cancer." (PMID 31608175, 2019). "Suppressing sST2 reduced ErbB2-induced cell motility in breast cancer cells." (PMID 31231372, 2019). "Interaction of YY1 with AP-2 transcription factor induces ERBB2 expression in breast cancer cells." (PMID 31824839, 2019). "Interestingly, we additionally found that miR-205-5p expression was significantly reduced in the ErbB2-overexpressing breast cancer cell lines stably expressing CLCN3 shRNA." (PMID 31608175, 2019). "In the same vein, we observed a lower prevalence of ERBB2 amplification in this breast cancer patient cohort compared to that in a general population (3 vs. 10–15%, respectively) but a higher incidence of ESR1 mutations associated with progression on hormone-based therapies." (PMID 31019892, 2019). "ErbB2 and ErbB3 co-overexpression decreases survival rate of breast cancer patients." (PMID 30621788, 2019). "Thus, in ErbB2-driven breast cancer, c-Src appears to activate mTORC1 via a mechanism independent of canonical RTK-driven pathways." (PMID 31263101, 2019). "Interestingly, a similar finding has been reported for the ERBB2-specific monoclonal antibody trastuzumab, used in ERBB2-positive breast cancer patients." (PMID 31273513, 2019). "However, within a panel of ERBB2+ breast cancer cell lines, trastuzumab only efficiently inhibited the growth of the high ERBB2-expressing ZR-75-30 cell line (IC50 0.2 μg/mL, ~ 1.3 nM)." (PMID 30898150, 2019).
breast cancer (continued). "In addition, ER+PR-HER2+ breast cancers also exhibited a lower ERBB2 amplification rate (59% vs. 85%, P = 0.017)." (PMID 31410192, 2019). "Five human epidermal growth factor receptor 2 (HER2/ERBB2/neu)-targeted therapies are currently approved by the Food and Drug Administration (FDA) for the treatment of HER2-positive (HER2+) breast cancers: trastuzumab, pertuzumab, trastuzumab emtansine (T-DM1), lapatinib, and neratinib." (PMID 31141894, 2019). "Of note, our study indicates that the anti-cancer effect is synergized by cotreatment with Herceptin, an ERBB2-targeted monoclonal antibody, plus Grb7 knockdown in ERBB2+ breast cancers, reflecting the tight correlation between Grb7 and ERBB2 in cancer progression and treatment." (PMID 31083325, 2019). "In addition, functional cooperation of miR-125a, miR-125b, and miR-205 can act together to suppress erbB2/erbB3 expression in breast cancer cells, which manifest a novel breast cancer treatment via miRNA-dependent or -independent mechanisms." (PMID 31301674, 2019). "Using quantitative readouts of signalling pathway activation and cell proliferation, we have examined their influence upon the mechanism of trastuzumab- and pertuzumab-mediated inhibition of cell growth in ERBB2-amplified breast cancer cell lines and a patient-derived xenograft model." (PMID 30898150, 2019). "[Poly (I:C)] has been shown to have direct apoptotic and growth inhibitory effects on various human cancer cell lines, and, furthermore, is capable of augmenting the anti-tumour effects of ErbB2 antibodies for breast cancer cell lines through a putative ADCC mechanism." (PMID 30781517, 2019). "Trastuzumab (anti-ErbB2 mAb), cetuximab and panitumumab (anti-EGFR mAbs) and rituximab (anti-CD20 mAb) are examples of mAbs of proved efficacy in the treatment of ErbB2+ breast cancers, colorectal carcinomas, head and neck cancers and B-cell cell malignancies, respectively." (PMID 30999624, 2019). "Indeed, short hairpin RNA-mediated knockdown of GRB7 expression reduces cancer proliferation and anchorage-independent growth in ERBB2/Grb7-overexpressing breast cancers." (PMID 31083325, 2019). "Additionally, breast cancers are typically classified as luminal, basal/myoepithelial or ERBB2- subtypes based on relation to cell types found in the normal breast." (PMID 31684899, 2019). "We have previously found that the class I HDAC inhibitor (HDACi), entinostat (also known as MS-275 or SNDX-275) specifically enhanced expression of miR-125a, miR-125b, and miR-205, which acted in concert to downregulate ErbB2 and ErbB3 in ErbB2-overexpressing breast cancer cells." (PMID 30961642, 2019). "Interestingly, while ERBB2 is frequently amplified in various malignancies, including breast cancer, gastric cancer, or colon cancer, GBCs have a substantial rate of ERBB2 mutations." (PMID 31795490, 2019). "Breast cancer is currently classified into five intrinsic subtypes, typically using immunohistological markers (estrogen receptor [ER], progesterone receptor [PR], HER2 gene, and/or ERBB2 protein status), tumor grade, and/or proliferation." (PMID 31315058, 2019). "Thus, ERBB2 is regulated by the BCLIN25-miR-125b-ERBB2 axis, and BCLIN25 is a bona fide MS-lincRNA in HER2 breast cancer." (PMID 31801944, 2019). "On the basis of these observations, CLCN3 may have the potential to be a novel therapeutic target for ErbB2-overexpressing breast cancers." (PMID 31608175, 2019). "However, while trastuzumab chemotherapy combinations are effective in improving survival in early-stage ERBB2+ breast cancer, approximately 25% of patients will relapse within 10 years." (PMID 30898150, 2019). "A similar mechanism has been reported in ERBB2-positive breast cancer." (PMID 30841549, 2019).